JUP (junction plakoglobin)
Description:
Common junctional plaque protein. The membrane-associated plaques are architectural elements in an important strategic position to influence the arrangement and function of both the cytoskeleton and the cells within the tissue. The presence of plakoglobin in both the desmosomes and in the intermediate junctions suggests that it plays a central role in the structure and function of submembranous plaques. Acts as a substrate for VE-PTP and is required by it to stimulate VE-cadherin function in endothelial cells. Can replace beta-catenin in E-cadherin/catenin adhesion complexes which are proposed to couple cadherins to the actin cytoskeleton (By similarity). May promote axon outgrowth and motor fiber repair via DSP-mediated recruitment to outgrowth tips (By similarity).
Synonyms: CTNNG; DP3; PDGB; PKGB; DPIII; PG
Tractability: Antibody: UniProt places it where antibodies can reach, with high confidence; its Gene Ontology location is reachable by antibodies, with high confidence; the Human Protein Atlas places it where antibodies can reach. PROTAC: ubiquitination databases record sites on it; its protein half-life has been measured.
Gene: Protein-coding gene on chromosome 17 (41,750,887 to 41,786,931, reverse strand). Ensembl gene ENSG00000173801.
Subcellular location: Cell junction, adherens junction; Cell junction, desmosome; Cytoplasm, cytoskeleton; Cell membrane; Cytoplasm; Cell junction; Nucleus; Cell projection, axon
Subcellular location (Human Protein Atlas): Cell Junctions; Plasma membrane; Vesicles
Pathways (Reactome):
Cell-Cell communication: Activation of STAT3 by cadherin engagement; Adherens junctions interactions; CDH11 homotypic and heterotypic interactions; Degradation of CDH1; Regulation of CDH1 Function; Regulation of CDH1 posttranslational processing and trafficking to plasma membrane; Regulation of CDH11 function; Regulation of CDH19 Expression and Function; SRC activates STAT3 in a quantitative manner, through Cadherin-11 (CDH11), RAC1 and gp130 (IL6ST)
Signal Transduction: CDC42 GTPase cycle; RHOA GTPase cycle; RHOB GTPase cycle; RHOC GTPase cycle; RHOH GTPase cycle; RHOJ GTPase cycle; RHOQ GTPase cycle; VEGFR2 mediated vascular permeability
Developmental Biology: Formation of the cornified envelope; Keratinization
Immune System: Neutrophil degranulation
Gene Ontology:
Molecular function: alpha-catenin binding; cadherin binding; cell adhesion molecule binding; cytoskeletal protein-membrane anchor activity; protein binding; protein phosphatase binding; transcription coactivator activity; cell adhesive protein binding involved in bundle of His cell-Purkinje myocyte communication; nuclear receptor binding; structural molecule activity
Biological process: bundle of His cell-Purkinje myocyte adhesion involved in cell communication; cell migration; cell-cell adhesion; cellular response to indole-3-methanol; desmosome assembly; detection of mechanical stimulus; negative regulation of blood vessel endothelial cell migration; positive regulation of angiogenesis; positive regulation of cell-matrix adhesion; positive regulation of protein import into nucleus; positive regulation of transcription by RNA polymerase II; protein localization to plasma membrane; regulation of cell population proliferation; regulation of heart rate by cardiac conduction; regulation of ventricular cardiac muscle cell action potential; canonical Wnt signaling pathway; endothelial cell-cell adhesion; positive regulation of axon extension; positive regulation of canonical Wnt signaling pathway; cell adhesion; positive regulation of protein localization
Cellular component: adherens junction; catenin complex; cell junction; cell-cell junction; cytoplasm; desmosome; extracellular exosome; focal adhesion; gamma-catenin-TCF7L2 complex; intercalated disc; nucleus; plasma membrane; protein-DNA complex; anchoring junction; axon; cornified envelope; cytoplasmic side of plasma membrane; cytoskeleton; cytosol; extracellular region; ficolin-1-rich granule lumen; hemidesmosome; specific granule lumen; zonula adherens; catenin-TCF7L2 complex; and 3 more
Genetic constraint (gnomAD): Loss-of-function variants: 27 observed, 69.91 expected, observed/expected ratio (o/e) 0.39, 90% interval 0.28 to 0.53. The upper end of that interval is the gene's LOEUF score, 0.53, which puts it in group 2 of 6, group 1 being the genes least tolerant of losing a copy. Missense variants: 869 observed, 1,052 expected, observed/expected ratio (o/e) 0.83, 90% interval 0.78 to 0.87. Synonymous variants: 401 observed, 448.38 expected, observed/expected ratio (o/e) 0.89, 90% interval 0.82 to 0.97.
Homologues: Orthologues: chimpanzee JUP (99% identical), macaque JUP (99% identical), dog JUP (99% identical), rabbit JUP (99% identical), mouse Jup (98% identical), pig JUP (98% identical), rat Jup (97% identical), guinea pig JUP (96% identical), tropical clawed frog jup (82% identical), zebrafish jupa (69% identical), zebrafish jupb (68% identical), Drosophila melanogaster arm (61% identical), and 1 more. Paralogues in human: CTNNB1 (68% identical), ARMC3 (19% identical), ODAD2 (17% identical), ANKAR (14% identical).
Diseases named in the same sentence as JUP in open-access papers:
JUP is named in the same sentence as 85 diseases in open-access papers, as found by Europe PMC text mining. Sharing a sentence is not in itself a finding about the gene and the disease. The quoted sentences say what the papers report.
breast carcinoma (14 papers, 2011 to 2025). "Further, JUP promotes distant metastasis in breast cancer by enhancing the formation of circulating tumor cell clusters." (PMID 33533127, 2021). "For breast cancer, decreased JUP expression was shown to lower cell–cell contact and thus to increase invasion and cancer cell dissemination in vivo." (PMID 33533127, 2021). "EMAT clusters displayed distinct expression profiles for CDH1, VIM, RHOA, and JUP, well-accepted biomarkers of epithelial (E), mesenchymal (M), amoeboid (A), and collective cell migration in breast cancer, respectively." (PMID 32641077, 2020). "Single cell analyses found the desmosomal constituent plakoglobin encoded by the junction plakoglobin JUP gene, overexpressed by 219 folds in CTC clusters as compared to single CTCs from breast cancers." (PMID 32290245, 2020). "Interestingly, a recent study found that high JUP expression enables tumor cells to adhere together and move as clusters into the bloodstream, facilitating metastasis and resulting in worse prognosis in breast cancer patients." (PMID 33102207, 2020). "JUP (junction plakoglobin) is a core desmosomal component and adhesion molecule with established roles in CTC cluster formation and metastasis in breast cancer." (PMID 41423632, 2025). "The top five hub genes for the hormone-like community were KRT18, JUP, KRT8, SH2D3A and PDLIM1; KRT18 and KRT8 are luminal markers in breast cancer while JUP (plakoglobin), SH2D3A and PDLIM1 are relatively undescribed in the context of cancer." (PMID 39556603, 2024). "The plakoglobin (JUP), KRT8, KRT18, KRT19, CLDN4, and EPCAM, which their role in breast cancer metastasis was demonstrated in previous studies, are EMT markers." (PMID 34801010, 2021). "JUP, part of the Armadillo protein family, crucial for cell adhesion and architecture, shows specificity by not being elevated in early-stage breast cancer." (PMID 39033780, 2024). "Conversely, some recent studies showed that metastatic breast cancer cells retain the expression of epithelial marker genes such as CDH1, KRT14 and JUP, which could contributed to generation of cancer cell clusters at distant organs of metastatic foci." (PMID 27258152, 2016). "We have discovered that junction plakoglobin (JUP) interacts with SOX4 in both the cytosol and the nucleus and the interaction between SOX4 and plakoglobin is significantly increased when prostate and breast cancer cells are stimulated with WNT3A." (PMID 22098624, 2011).
cardiomyopathy (8 papers, 2016 to 2025). A disease of the heart muscle or myocardium proper. "Besides the hub genes of MYBPC3, MYH7, and DSP, these subnetworks also include several genes that have been implicated in cardiomyopathy, such as TPM1, ACTC1, DES, TCAP, JUP, and DSG2." (PMID 32344918, 2020).
colorectal cancer (7 papers, 2013 to 2023). A primary or metastatic malignant neoplasm that affects the colon or rectum. "Similarly, the JUP gene encoding for the β-catenin homolog, junction plakoglobin (also called γ-catenin), is also shown to be a dependence gene in a subset of 20q11.21 amplified colorectal cancer cell lines." (PMID 34577783, 2021). "Furthermore, JUP was implicated in testicular germ cell tumors, and colorectal cancers." (PMID 33102207, 2020). "For example, suppression of the junction plakoglobin (JUP) resulted in the repression of colorectal cancer cell migration and invasion." (PMID 37654625, 2023). "In addition, several genes included in both models, such as JUP and ESM1, were reported to be associated with the prognosis of colorectal cancer patients by other researchers, which proved that the results of both models were reliable." (PMID 33628243, 2021). "Inhibitor of β‐catenin and T‐cell factor (ICAT) promotes colorectal cancer (CRC) cell migration and invasion by interacting with the junction plakoglobin (JUP) and via the NF‐κB signaling pathway in CRC." (PMID 36036768, 2022).
Arrhythmia (6 papers, 2017 to 2026). Any cardiac rhythm other than the normal sinus rhythm. "Disruption of the connexome alters the activity of sodium channels including SCN5A and contributes to arrhythmias in ARVC patients with PKP2 or JUP mutations." (PMID 38370698, 2024). "We also identified five potentially pathologic variants in genes associated with cardiac arrhythmia, including KCNMB1, KCNIP1, DPP6, JUP, F2, and TUBA3D that were identified in SUDEP patients but not present in our living epilepsy cases." (PMID 29619247, 2018). "JUP is a crucial desmosomal protein in the heart whose dysfunction may lead to cardiomyocyte detachment, signaling transduction, and cardiac fibrosis and arrhythmias." (PMID 38297207, 2024).
melanoma (6 papers, 2016 to 2026). A malignant, usually aggressive tumor composed of atypical, neoplastic melanocytes. "Overexpression of JUP in melanoma has been shown to upregulate VEGFA expression, and tumors with elevated JUP display a larger area of CD31-positive staining, indicating increased angiogenesis." (PMID 41583504, 2026). "Our results suggest the presence of Plakoglobin (JUP)/Anterior Gradient 2 (AGR2)/LY6/PLAUR Domain Containing 3 (LYPD3) pro-oncogenic signaling in melanoma." (PMID 37924160, 2023). "It was shown that hyperactivation of the JUP/AGR2/LYPD3 signaling axis contributes to the regulation of melanoma cell stemness and promotes glycolysis through a Glucose Transporter Type 1 (GLUT1)-dependent pathway." (PMID 37924160, 2023). "We stained and visualized the cytoskeleton using phalloidin and found that JUP/AGR2/LYPD3 can help melanoma cells form pseudopodia." (PMID 37924160, 2023). "In the present study, we demonstrated that upregulation of JUP/AGR2/LYPD3 signaling promotes melanoma cytoskeleton remodeling and stimulates the formation of new pseudopods." (PMID 37924160, 2023). "We demonstrated that JUP regulates Anterior Gradient 2 (AGR2)/LY6/PLAUR Domain Containing 3 (LYPD3) to maintain melanoma stemness and promotes glycolysis." (PMID 37924160, 2023). "The JUP/AGR2/LYPD3 signaling axis plays an important role in the malignant features of melanoma." (PMID 37924160, 2023). "This study extends the biological significance of the JUP/AGR2/LYPD3 signaling axis to melanoma." (PMID 37924160, 2023). "We confirmed that the JUP/AGR2/LYPD3 signaling axis promotes F-actin expression, remodels the cytoskeleton and confers a robust invasive phenotype to melanoma cells." (PMID 37924160, 2023). "Both JUP and DSP were identified to be upregulated in melanoma cell lines, where they significantly increase tumor burden, VEGF-A, reduced IL-33, and angiogenesis, thus emphasizing their PT roles." (PMID 37834160, 2023). "In TCGA-SKCM, we found that the collective up-regulation of JUP, PKP1, and PKP3 could define a distinct catenin subgroup in melanoma (C2), which possesses poorer survival and more aggressive clinical features compared to another subgroup (C1)." (PMID 37924160, 2023). "Interestingly, there are 2 RNA expression patterns of catenins in TCGA-SKCM, where PKP1, JUP, PKP3 belong to the same group and are deleterious for survival in melanoma patients." (PMID 37924160, 2023). "Our findings suggest that the JUP/AGR2/LYPD3 signaling axis plays an important role in melanoma, but its in-depth mechanism of action is still lacking." (PMID 37924160, 2023). "Considering that JUP is a homologue of β-catenin and is closely related to β-catenin in many cases to concertedly regulate cell fate, we speculate that there may be a mechanism of JUP/AGR2/LYPD3 signaling regulation in melanoma." (PMID 37924160, 2023).
Naxos disease (5 papers, 2014 to 2023). A recessively inherited condition with arrhythmogenic right ventricular dysplasia/cardiomyopathy (ARVD/C) and a cutaneous phenotype, characterized by peculiar wooly hair and palmoplantar keratoderma. "Loss-of-function mutation of JUP has been associated with Naxos disease, which is also characterized by palmoplantar keratoderma." (PMID 37279397, 2023). "As a second approach to compromise Jupa function, we injected a human JUP mRNA with a mutation that causes naxos disease." (PMID 29376824, 2018). "Naxos disease is caused by a homozygous pathogenic variant in the plakoglobin gene (JUP), leading to ACM (100% penetrance), woolly hair, and palmoplantar keratoderma, whereas in Carvajal syndrome, a recessive homozygous pathogenic variant in the desmoplakin gene (DSP) gives rise to similar symptoms." (PMID 35008484, 2021). "Most of the previously identified gene mutations that underlie ARVC (ARVC 8, 9, 10 and 12 and Naxos disease) are mutations of genes encoding desmosomal proteins: Plakophilin2 (PKP2), Desmoplakin (DSP), Desmoglein2 (DSG2), Desmocollin2 (DSC2) and Junction Plakoglobin (JUP)." (PMID 25343256, 2014).
bladder cancer (4 papers, 2021 to 2024). "In line with this, the restoration of JUP expression could inhibit bladder cancer cell migration and tumor progression, and patients with bladder cancer with low JUP expression consistently exhibit poor survival rates." (PMID 39132499, 2024). "JUP deletion leads to reduced cell contact, increased invasion, and bladder cancer cell metastasis." (PMID 39132499, 2024). "For bladder cancer patients with bone metastasis, JUP could down-regulating the ITGB4 − 43,489− ES by the pathway of glycosphingolipid biosynthesis ganglio series which was also related to the prognosis." (PMID 34402716, 2021).
leukemia (4 papers, 2021 to 2026). A malignant (clonal) hematologic disorder, involving hematopoietic stem cells and characterized by the presence of primitive or atypical myeloid or lymphoid cells in the bone marrow and the blood. "A parallel network, consisting of Wnt-JUP-MYC-BIRC5 axis, operates in BCR::ABL1-positive B-cell ALL, where JUP acts as a key driver required for leukemia maintenance." (PMID 41596324, 2026). "Since we saw relevant differences in the SALL2 and JUP expressions in leukemia patients in contrast to healthy bone marrow samples, we determined whether the expressions of these genes were related to better overall survival." (PMID 36428851, 2022). "High expression of JUP, NT5C3B, MYC, GATA3, PTK7, CNP, and ICOSLG clearly differentiated the leukemia from the non-leukemia group." (PMID 41596324, 2026). "Importantly, JUP, NT5C3B, MYC, and GATA3, PTK7, CNP, and ICOSLG differentiated both non-pathological conditions (non-leukemia and MRD-negative) from leukemia samples." (PMID 41596324, 2026).
lung carcinoma (4 papers, 2018 to 2024). "HDAC7 also inhibits the expression of the tumour suppressor gene JUP (Junction plakoglobin) to promote lung cancer cell growth and metastasis." (PMID 35626663, 2022). "According to our observation presented above and considering the facts that DSP and JUP can suppress lung cancer progression by inhibition of the Wnt/β-catenin signaling pathway, we hypothesized that SOX30 can suppress the Wnt/β-catenin signaling pathway through upregulation of DSP and JUP." (PMID 29855376, 2018). "Our study confirmed that Jinfukang has inhibitory effects on the clustering and invasion of lung cancer CTCs, mainly by regulating the EGFR-mediated cytoskeleton regulation pathway to downregulate the expression of JUP protein." (PMID 37723875, 2023). "The expression of SOX30, DSP, JUP and DSC3 were detected in lung cancer cell lines, lung tissues of mice and patients’ tissues by qPCR, WB, Immunofluorescence and Immunohistochemistry." (PMID 29855376, 2018). "Among these 8 desmosomal genes, the most obvious change in expression is three tumor suppressor genes for lung cancer, DSP, JUP and DSC3." (PMID 29855376, 2018). "To further determine the correction between SOX30 and these genes, we tested for expression of SOX30, DSP, JUP and DSC3 in human lung cancer tissues and adjacent tissues." (PMID 29855376, 2018). "In lung cancer, SOX4 expression is probably related to the overregulation of WNT5A; then, SOX4, FOXM1, TCF3, and JUP might form a stable protein complex with other factors and co-factors for the regulation of transcriptional targets." (PMID 39228892, 2024). "The expression of DSP and JUP are reduced or absent in lung cancer and re-expression results in reduction of cell growth and migration by suppressing the Wnt signaling pathway in lung cancer." (PMID 29855376, 2018).
arrhythmogenic right ventricular cardiomyopathy (3 papers, 2023 to 2025). "The presence of multiple pathogenic variants in desmosomal genes (DSC2, DSG2, DSP, JUP, and PKP2) in patients with arrhythmogenic right ventricular cardiomyopathy (ARVC) has been linked to a severe phenotype." (PMID 37418234, 2023).
prostate carcinoma (3 papers, 2011 to 2022). A carcinoma that arises from epithelial cells of the prostate gland. "Hsa-miR-133a-3p, miR-1-3p, GOLPH3 and JUP are functional drivers of PCa and may be their combination is a promising diagnostic biomarker panel for prostate cancer." (PMID 36387263, 2022). "Using LC-MS/MS proteomic analysis, we identified a novel SOX4 binding protein, junction plakoglobin, in LNCaP prostate cancer cells." (PMID 22098624, 2011).
viral infections (3 papers, 2022 to 2025). "The 8-gene signature included three genes over-expressed in bacterial infections (SMARCD3, ICAM1, EBI3; “bacterial genes”) and five over-expressed in viral infections (JUP, SUCLG2, IFI27, FCER1A, HESX1; “viral genes”)." (PMID 36543117, 2022). "Silencing JUP has been shown to disrupt actin organization within the cytoskeleton, and the cytoskeleton plays a critical role in multiple stages of viral infection, including the transport or assembly of viral proteins and particles, immune evasion, and cell-to-cell fusion." (PMID 40431638, 2025). "Of the viral genes, IFI27 and JUP are known to be upregulated in response to viral infection." (PMID 36543117, 2022). "However, the functions of JUP in viral infection remain largely unexplored." (PMID 40431638, 2025). "Although JUP’s role in viral infection has not been defined, its influence on actin dynamics suggests it could impact RSV assembly and budding." (PMID 40431638, 2025).
channelopathy (2 papers, 2023 to 2024). Channelopathies are a group of diseases caused by the dysfunction of ion channel subunits or their interacting proteins. "The variants included three channelopathy-associated genes (RYR2, CACNA1C, and ANK2), three HCM- or DCM-associated genes (MYH7, LDB3, and PRKAG2), five ACM-related genes (PKP2, JUP, DSG2, DSP, and TMEM43), and two cardiac transcription factor genes (TBX5 and GATA4)." (PMID 39272661, 2024).